ALB (albumin)
Diseases named in the same sentence as ALB in open-access papers (continued):
Sharing a sentence is not in itself a finding about the gene and the disease.
Insulin resistance (continued). "The highest Hb quintile had the highest BMI, the highest BP values and insulin resistance scores, the least favorable lipid profile, and the highest albumin levels in both sexes." (PMID 38643302, 2024). "Of several measures of hyperinsulinemia, insulin resistance, glucose tolerance, body bioimpedance, waist circumference, and urine albumin, one parameter from each category was included in the PC analysis." (PMID 39593205, 2024). "Given that the extent of insulin resistance is closely associated with the likelihood of developing CKD, it follows that insulin resistance contributes to elevated urinary albumin excretion." (PMID 38559692, 2024). "The effects resulted in improved intake and digestibility of nutrients, accompanied by changes in the responses to serum glucose, insulin, albumin, and cholesterol, indicating improved glucose tolerance and reduced insulin resistance." (PMID 39682453, 2024). "In Random Forest, homeostatic model assessment for insulin resistance, serum uric acid, serum albumin, gamma glutamyl transferase, and triiodothyronine/thyroxine ratio were positioned in the upper ranks of variable importance." (PMID 38941283, 2024). "Vitamin D3 dose-dependently improves glucose control parameters, as shown by the reduction of fasting blood glucose (FBG), oral glucose tolerance test (OGTT), glycated albumin, insulin levels, and markers of insulin resistance (HOMA-IR)." (PMID 37324274, 2023). "As FFA molecules are hydrophobic and depend upon binding to albumin for dissolution/transport in the blood, our efforts to understand FFA metabolism in the context of insulin resistance and hepatic steatosis are focused on studying albumin." (PMID 37432201, 2023). "Its biological characteristics included increased insulin resistance, and elevated urea, albumin and CYP450, consistent with the clinical features of human NAFLD." (PMID 35276900, 2022). "In this work, normal rats treated with albumin-AGE for 12 weeks developed insulin resistance as well as a decreased Scl2a4 mRNA expression and GLUT4 protein content." (PMID 35883827, 2022). "In conclusion, the present study demonstrated ER-PA resulted in significant ameliorate of urinary albumin excretion, oral glucose tolerance, and insulin resistance index." (PMID 34281284, 2021). "We aimed to investigate the changes of serum adiponectin and glycated albumin (GA) levels in gestational diabetes mellitus patients and their relationship with insulin resistance." (PMID 33083291, 2020). "Blood glucose, fasting insulin levels, insulin resistance index, and 24-h urinary albumin excretion (UAE) were measured." (PMID 31338070, 2019). "Previous studies have demonstrated that urinary albumin level or decreased eGFR is related to insulin resistance, inflammation, oxidative stress, and vascular endothelial dysfunction." (PMID 31828155, 2019). "Glycated albumin, insulin, C‐peptide, proinsulin and homeostatic model assessment of insulin resistance were significantly reduced." (PMID 31033218, 2019). "Increased stages of fibrosis were primarily associated with higher levels of HOMA2-insulin resistance (IR), procollagen type I propeptide (P1NP), lower osteocalcin, albumin-corrected calcium, parathyroid hormone, vitamin D, male sex, and higher age." (PMID 26989059, 2016). "Serum biochemistry was analyzed including serum albumin-corrected calcium (Cac), insulin resistance (IR, using homeostasis model assessment [HOMA]), fibrinogen, and homocysteine." (PMID 27310988, 2016). "Two markers novel to this current report, increases of leptin (satiety hormone) and afamin (related to albumin), likely also reflect metabolic disturbances by corticosteroids, possibly downstream of insulin resistance." (PMID 27530235, 2016). "Fatty liver index was positively associated with baseline blood pressure, homeostasis model assessment of insulin resistance, urinary albumin/creatinine excretion, and high sensitivity C-reactive protein." (PMID 26618774, 2015).
Insulin resistance (continued). "Our study excluded serum insulin resistance and urinary albumin excretion in the respective definitions." (PMID 24171882, 2013). "Fibrinogen, CRP, and C3 were positively, whereas albumin was inversely correlated with abdominal adiposity and insulin resistance." (PMID 21822486, 2012). "Insulin resistance was estimated using the triglyceride-glucose (TyG) index, and renal function was evaluated by estimated glomerular filtration rate (eGFR) and urinary albumin-to-creatinine ratio (UACR)." (PMID 41718366, 2026). "Chronic hyperglycemia promotes tumor proliferation while impairing immune surveillance, and induces insulin resistance and albumin glycation that may reduce its antioxidant capacity." (PMID 41299673, 2025). "Furthermore, HLB was shown to significantly improve DN, which is characterized by elevated blood glucose, insulin resistance, increased renal volume, elevated glomerular filtration rate, and abnormal urinary albumin excretion in diabetic mice." (PMID 40170727, 2025). "Similarly, CB1 antagonist SR141716 (also known as Rimonabant) improved insulin resistance and decreased albumin excretion and proinflammatory cytokines in diabetic kidneys." (PMID 40558673, 2025). "Primary endpoints included stress response markers (serum cortisol, homeostatic model assessment of insulin resistance), nutritional parameters (prealbumin, albumin, blood urea nitrogen), and clinical outcomes (time to gastrointestinal recovery, length of hospital stay)." (PMID 40696632, 2025). "The level of albumin, was shown to correlate strongly with the state of insulin resistance." (PMID 38702370, 2024). "BCAAs could improve albumin synthesis and insulin resistance, as well as the prevention of the occurrence of HCC and clinical decompensation in cirrhotic patients, resulting in an improvement in these patients." (PMID 37763625, 2023). "An alternative pathway could involve reduced albumin levels (associated with lower CD4 counts in the non‐pregnant population), given the link between high albumin levels and insulin resistance." (PMID 37012900, 2023). "Furthermore, inhibition of TNF-α decreased the excretion of urinary albumin, partially indicating the mitigation of insulin resistance." (PMID 35855831, 2022). "Serum alanine aminotransferase, aspartate aminotransferase, gamma‐glutamyl transpeptidase, platelets, albumin, triglyceride, cholinesterase, fasting plasma insulin, homeostasis model of assessment of insulin resistance, and other markers have been used as indicators of liver conditions." (PMID 34463983, 2021). "Higher serum albumin levels and insulin resistance have also been associated in nondiabetic populations without kidney disease." (PMID 30786864, 2019). "In vivo, AGE-albumin induced whole-body insulin resistance; decreased (~30%) Slc2a4 mRNA and GLUT4 protein content; and increased (~30%) the nuclear content of nuclear factor NF-kappa-B p50 subunit (NFKB1), and cellular content of 78 kDa glucose-regulated protein (GRP78)." (PMID 29802324, 2018). "Our hypothesis that this insulin resistance involves a direct effect of AGE-albumin in soleus muscle was supported by the detection of reduced expression of Ddost gene." (PMID 29802324, 2018). "Insulin resistance was correlated with fasting levels of insulin and leptin/adiponectin (r = 0.913); of insulin, retinol binding protein 4 and leptin/adiponectin (r = 0.903); and of insulin, glycated albumin, and leptin/adiponectin (r = 0.913)." (PMID 29610560, 2018). "Since Albumin synthesis is sensitive to insulin, they speculated that reduced serum albumin concentrations and biosynthesis is a result of high fat diet- induced insulin resistance." (PMID 28482801, 2017). "The insulin resistance observed in rats chronically treated with AGE-albumin may be more related to skeletal muscle damage." (PMID 29018354, 2017).
Insulin resistance (continued). "Insulin resistance and senescence were confirmed by reduced glucose uptake and increased β-Galactosidase Staining and increased p-H2A.X (Ser139) levels after 24 h of co-incubation with bovine serum albumin (BSA) conjugated palmitic acid (PA; 50 μM) and 278 mM D-galactose (D-Gal) in human AC16 cells." (PMID 41604031, 2026). "By regulating serum Ca and albumin, insulin resistance may be alleviated." (PMID 41019331, 2025). "Therefore, it is plausible that dotinurad may also lower urinary albumin by improving insulin resistance in hyperinsulinemic patients." (PMID 40839334, 2025). "However, there was a significant correlation between serum albumin levels and insulin resistance in patients with Mets, whereas the association was not seen in patients without Mets." (PMID 36983240, 2023). "Subsequently, other studies noted a distinct presentation of de novo NAFLD post pancreatectomy that may be characterized by lack of insulin resistance, lower cholesterol and albumin, decreased BMI (16.3–20.1 kg/m2) and associated with EPI." (PMID 36705353, 2023). "This study further suggests the possibility that repeated bouts of transient postprandial hyperglycemia could gradually induce the formation of sufficient levels of albumin-AGE to induce a more permanent long-term insulin resistance, as can be found in pre-diabetes." (PMID 35883827, 2022). "Albumin-bound NEFA are filtered through the glomeruli and reabsorbed by the proximal tubulus, a process that can directly and aggressively contribute to renal damage, promote renal insulin resistance, cause renal lipid accumulation, and activate proinflammatory pathways." (PMID 31886287, 2019). "However, the association between serum albumin and glycemic alteration in subjects without evident insulin resistance has rarely been examined." (PMID 28430803, 2017). "Markers of glycemic control and insulin resistance (HbA1c, HOMA-IR) were markedly increased in MetS (p < 0.05), whereas albumin was slightly higher in this group (p = 0.002)." (PMID 41595473, 2026). "We measured parathyroid hormone (PTH), 25-hydroxyvitamin D, bone mineral density (BMD), hemoglobin A1c (HbA1c), serum albumin (ALB), and Homeostatic Model Assessment for Insulin Resistance (HOMA-IR)." (PMID 40313432, 2025). "Because we did not measure grip strength, calf circumference, serum albumin, pre-albumin or other nutritional biomarkers, we cannot exclude the possibility that the elevated risk observed in the lowest TyG-BMI stratum is driven chiefly by reverse causation rather than by insulin resistance per se." (PMID 41368181, 2025). "Significant differences were observed among these groups in body weight; BMI; WC; systolic blood pressure; and albumin, FBG, HbA1c, TG, HDL-C, AST, ALT, insulin, insulin resistance, and hs-CRP levels." (PMID 39408311, 2024). "Furthermore, insulin resistance is associated with a significant increase in CVD incidence and mortality, and therefore the high insulin sensitivity (e.g., as seen in the albumin knockout mouse) may be protective from CVD." (PMID 35238481, 2022). "From a finally selected sample size of 227 male and female subjects we evaluated their anthropometric data, HbA1c, lipid profile including calculated sdLDLc, urine albumin creatinine raito(UACR) and insulin resistance (HOMAIR)." (PMID 30323862, 2018). "The endpoints of the study were the insulin resistance (IR), the prognostic inflammatory and nutritional index (PINI) and the C-reactive protein (CRP)/albumin ratio." (PMID 21668975, 2011). "Second, we comprehensively evaluated multiple dimensions of metabolic health simultaneously, including glycemic control (glucose, glycated albumin, and HOMA-IR), insulin resistance, lipid profiles, body composition, and satiety markers, rather than focusing on isolated parameters." (PMID 40944189, 2025).
Insulin resistance (continued). "Furthermore, there was a positive association between asprosin levels and various factors such as albumin, FBS, homeostasis model assessment of insulin resistance (HOMA-IR), and TG levels." (PMID 38750109, 2024). "Fasting blood glucose levels, serum fasting insulin levels, Homeostatic Model Assessment for Insulin Resistance (HOMA-IR), serum triglycerides, cholesterol, low-density lipoprotein-cholesterol, serum and urinary albumin, and creatinine and urea levels were measured." (PMID 38541120, 2024). "NADP negatively correlates with insulin resistance indices, the glucose to insulin ratio (GLU:INS) and RQUICKI and positively with TBIL, GGT, ALB and LFI values in cows receiving niacin, while in the control group cows showed a negative correlation with GGT and a positive correlation with urea." (PMID 35739861, 2022). "The negative correlation between total 25 hydroxyvitamin D and insulin resistance after adjustment for creatinine (urine), albumin (urine), and cholesterol was consistent in most subgroups." (PMID 36079784, 2022). "Moreover, IGF-I has a well-described function in lowering insulin resistance, that plays a pivotal role in the pathogenesis of NAFLD and has been shown to increase albumin levels after 120 days of subcutaneous administration in cirrhotic patients." (PMID 30063751, 2018). "The H2 treatment had little effect on these animal models with hyperinsulinemia and insulin resistance: neither fasting glucose nor glycated albumin differed significantly in high-fat diet-induced diabetic or db/db mice." (PMID 23326534, 2013). "In patients with early DN (urine albumin-to-creatinine ratio [UACR] >30 mg/g and estimated glomerular filtration rate (eGFR) >90 ml/min/1.73 m2), Metformin treatment reduced body mass index (BMI) and homeostatic model assessment for insulin resistance (HOMA-IR)." (PMID 41203135, 2025). "HDL-c (B=-0.168, p=0.005) and albumin (B=-0.168, p=0.005) showed significant negative associations with METS-IR, indicating that higher HDL-c and albumin levels are beneficial in reducing insulin resistance." (PMID 39469359, 2024). "The results showed that PTR could alleviate pancreatic tissue damage, significantly decrease fasting blood glucose (FBG), fasting serum insulin (FINS), homeostasis model assessment insulin resistance (HOMA-IR), urinary glucose (UGLU), and urinary albumin/creatinine ratio (UACR)." (PMID 38005193, 2023). "Measurement of urinary albumin excretion and insulin resistance was not done in our study, which may underestimate MetS using WHO definition." (PMID 35132136, 2022). "Percent change in serum albumin levels remained an independent protective factor for incident prediabetes (models 1–5) in subjects with normal BMI and waist circumference and who did not have insulin resistance." (PMID 28430803, 2017). "Unlike TgKO mice which are prone to HFD-induced insulin resistance, HFD-fed HKO mice developed insulin resistance, glucose intolerance, and pyruvate intolerance to a similar degree as albumin-Cre and SH2B1f/f mice fed a HFD." (PMID 24358267, 2013).
endothelial dysfunction (155 papers, 2004 to 2026). In vascular diseases, endothelial dysfunction is a systemic pathological state of the endothelium (the inner lining of blood vessels) and can be broadly defined as an imbalance between vasodilating and vasoconstricting substances produced by (or acting on) the endothelium. "Serum albumin provides vascular protection through anti-inflammatory, antioxidant, and antithrombotic mechanisms, while its deficiency induces endothelial dysfunction and prothrombotic states." (PMID 41377920, 2025). "In fact, the glycation of albumin is implicated in the pathogenesis of various vascular complications associated with DM, contributing to endothelial dysfunction." (PMID 41226224, 2025). "Albumin is a negatively regulated acute-phase reactant that decreases in response to infection, causing endothelial dysfunction and exacerbating fluid shifts, ultimately leading to adverse clinical outcomes." (PMID 41270012, 2025). "Albumin plays a vital role in maintaining capillary membrane stability and fluid balance and provides protective effects against endothelial dysfunction caused by inflammation and oxidative stress." (PMID 40606134, 2025). "This sustains the loss of urinary albumin, a protein with antioxidant properties, while maintaining the vicious cycle of inflammation, glomerular injury, and endothelial dysfunction." (PMID 40375997, 2025). "Low serum albumin has been implicated in impaired nitric oxide synthesis, vascular narrowing, sodium accumulation, and widespread endothelial dysfunction, all of which elevate blood pressure." (PMID 41008514, 2025). "Serum albumin, a potential marker of endothelial dysfunction and protein loss, has been proposed as a severity indicator in PE." (PMID 40648529, 2025). "Decreased serum albumin is associated with endothelial dysfunction, elevated blood viscosity, and platelet aggregation." (PMID 40322371, 2025). "Elevated CRP/Alb indicates chronic low-grade inflammation, combining increased hepatic CRP synthesis and decreased albumin production, both linked to insulin resistance and endothelial dysfunction." (PMID 41302334, 2025). "It is conceivable that early repeated exposure of MG adducts to RAGE in the kidneys can lead to prolonged endothelial dysfunction, causing impairments in the glomerular filtration rate, and enhanced albumin excretion as a result." (PMID 38247509, 2024). "Another study demonstrated a strong association between endothelial dysfunction, inflammatory activity, and increased urinary albumin excretion over a 10-year follow-up." (PMID 39727658, 2024). "The potential mechanisms linking CIN and serum albumin levels revolve around oxidative stress, inflammation, and endothelial dysfunction, collectively predisposing individuals to CIN." (PMID 38561791, 2024). "The presence of endothelial dysfunction, elevated glomerular pressure, and inflammation results in increased excretion of albumin by causing damage to the glomerular membrane." (PMID 36498617, 2022). "Serum albumin precatheterization can increase the risk for CI-AKI due to its relationship with endothelial dysfunction and background inflammatory response." (PMID 33414964, 2020). "Albuminuria, the pathological excretion of urinary albumin, reflects a state of vascular inflammation and generalized endothelial dysfunction causing further damage to microvessels." (PMID 31356602, 2019). "Higher WWI might reflect early-stage metabolic disruptions causing renal microvascular stress, endothelial dysfunction, and consequent albumin leakage." (PMID 40700436, 2025). "Herein, the prognosis of SSNHL may be closely linked to decreased ALB concentration, which may be due to impaired labyrinthine perfusion caused by endothelial dysfunction." (PMID 41411727, 2025). "As serum albumin falls, especially in inflammation-linked cardiovascular states, endothelial dysfunction might arise, boosting vessel leakiness." (PMID 41536368, 2025).